VWF (von Willebrand factor)
Diseases named in the same sentence as VWF in open-access papers (continued):
Sharing a sentence is not in itself a finding about the gene and the disease.
endothelial dysfunction (continued). "cfDNA levels correlated with markers of endothelial dysfunction (hsCRP P = 0.0497) and vWF (P = 0.0005) but not with proinflammatory cytokines in patients with CKD." (PMID 25371664, 2014). "Despite the significant increase in vitamin D levels in the cholecalciferol group, there was no reduction in markers of endothelial dysfunction including D-dimer, von Willebrand factor, fibrinogen and interleukin (IL) 8 or C reactive protein." (PMID 25006678, 2014). "Several other important biomarkers of endothelial dysfunction including Endothelin-1 and von Willebrand factor were not examined." (PMID 24339964, 2013). "So far there are no reports on correlation between LOXL1 activation and endothelial dysfunction, vascular injury nor vWF/selectins." (PMID 22593709, 2012). "We also measured plasma von Willebrand factor and PAI-1, as markers for endothelial dysfunction." (PMID 21283820, 2011). "The vWF-CBA may serve as a rapid, standardized tool for assessing endothelial dysfunction." (PMID 40508203, 2025). "While ICU patients tend to show more pronounced endothelial dysfunction due to acute illness and hemodynamic instability, non-ICU patients with elevated vWF may still be at risk of thrombotic events, albeit to a lesser extent or over a longer timeline." (PMID 41311551, 2025). "Elevated levels of factor VIII and von Willebrand factor were found in patients with CTEPH, suggesting their role in its development; however, this finding also might be a marker of chronic inflammation and endothelial dysfunction in this disease." (PMID 41300788, 2025). "Besides those functional parameters, there are several other biomarkers of endothelial dysfunction, including parameters of the arginine metabolism, endothelial microparticles (EMP) or von Willebrand factor (vWF), which have been investigated in SSc and were associated with disease complications." (PMID 40627153, 2025). "As VWF is an acute phase protein, increased levels may not directly reflect endothelial dysfunction." (PMID 39524447, 2024). "Additionally, the measurement of vWF, s-ICAM-1 and sCD-40L might be suggested in patients with heart failure to confirm endothelial dysfunction and provide personalized therapy." (PMID 35886486, 2022). "To measure endothelial dysfunction, we documented decreased production of eNOS and KLF2, a zinc finger family of transcription factors and bona-fide master regulator of endothelial maintenance function, and increased levels of endothelial cell surface von-Willebrand Factor." (PMID 35355507, 2022). "RT-PCR of liver sinusoidal endothelial cells showed a markable increment of von Willebrand Factor (vWF), thrombomodulin(TM), intercellular adhesion moleclar-1(ICAM-1), and vascular endothelial growth factor(VEGF) after TGF-β1 treatment, suggesting the involvement of endothelial dysfunction." (PMID 36225950, 2022). "The endothelial dysfunction was manifested by the induction of proinflammatory cytokines and prothrombotic mediators, like vascular cell adhesion molecule-1 (VCAM-1) and von Willebrand Factor (vWF), along with suppression of endothelial nitric oxide synthase (eNOS)." (PMID 35906216, 2022). "In addition, possible RSV-driven modulation of endothelial dysfunction markers was investigated, including intercellular adhesion molecule-1 (ICAM-1), von Willebrand factor (vWF), and Caspase-3, (CASP-3), in endothelial cells and umbilical arteries from patients with PE." (PMID 36358483, 2022). "In addition, RSV increased total antioxidant capacity and downregulated endothelial dysfunction biomarkers, such as intercellular adhesion molecule-1 (ICAM-1), von Willebrand factor (vWF), and Caspase-3, (CASP-3), in endothelial cells and umbilical arteries from PE patients." (PMID 36358483, 2022).
endothelial dysfunction (continued). "The gene transcription levels of von Willebrand factor (vWF), endothelin (ET), thrombomodulin (THBD), granular membrane protein 140 (GMP140), and intercellular cell adhesion molecule-1 (ICAM-1) related to endothelial dysfunction were all significantly increased." (PMID 34576058, 2021). "Based on our study and previous studies, it appears cardiomyopathy is not the reason for increased vWF : Ag concentration in hyperthyroid cats and could indicate endothelial dysfunction as a mechanism of thrombogenesis in hyperthyroid cats." (PMID 34590754, 2021). "Based on these findings, evaluating both the VWF/ADAMTS13 axis, along with thrombin and plasmin generation, could provide insight into the extent of endothelial dysfunction as well as the plasmatic imbalance in coagulation and fibrinolysis potential, particularly for at-risk patient populations." (PMID 35087853, 2021). "Since elevated von Willebrand factor (VWF) and factor VIII (FVIII) levels have been described as acute phase reactants that may indicate endothelial dysfunction and inflammation in different settings, including chronic autoimmune diseases, they could serve as potential candidate biomarkers of cGvHD." (PMID 33995421, 2021). "However, the evolution of von Willebrand factor, a marker of endothelial dysfunction, was not different between groups." (PMID 29445877, 2018). "Indeed, a significant correlation between VWF and INF-γ was observed in this study, which indicates that the interrelation between inflammation and endothelial dysfunction may be involved in the pathogenesis of diabetic nephropathy." (PMID 26770985, 2016). "Two of these proteins may be markers of endothelial dysfunction, such as von Willebrand Factor and endothelin converting enzyme 1 (not shown)." (PMID 27165192, 2016). "The absence of modification in both CD146 and the vWF, two biomarkers of endothelial dysfunction indicates that the accumulation of the fibronectin observed in the present experiments results from its in situ synthesis by the extracellular matrix rather than an accumulation of the circulating form." (PMID 26696902, 2015). "The admission levels of sPsel and VWF are greatly influenced by the presence of coagulopathy such that the relatively lower levels of these parameters in trauma patients often do not predict less platelet/endothelial dysfunction or a better outcome." (PMID 24034700, 2013). "Inflammatory biomarkers (CRP, IL-6, fibrinogen), plasma viscosity, endothelial dysfunction markers (VWF, t-PA), and coagulation factors (VIII and IX, but not VII) were significantly higher in cases of MI/CHD death, but not in cases of incident angina compared with those who were CHD event free." (PMID 19682232, 2009). "In the context of non-ICU patients, elevated vWF levels might reflect a less severe or early manifestation of endothelial dysfunction, which could be triggered by various conditions such as chronic inflammation, comorbidities (e.g., hypertension and diabetes), or vascular risk factors." (PMID 41311551, 2025). "The biomarkers for endothelial dysfunction, including VWF, factor VIII, and soluble thrombomodulin levels, were significantly elevated in convalescent COVID-19 patients compared with those for the controls, suggesting that endothelial dysfunction may contribute to long COVID-19 pathogenesis." (PMID 39199353, 2024). "The lack of significant rises in vascular biomarkers (sVCAM-1, vWf, and PTX3) with increasing disease activity in our patients with RA may suggest that the presence of RA itself-rather than the magnitude of concomitant inflammatory activity-underlies endothelial dysfunction." (PMID 24864133, 2014). "A further limitation of our study is the absence of endothelial biomarker data (such as vWF, endothelin, sE-selectin, and VEGF), which could have provided additional insight into the mechanisms of endothelial dysfunction in MIS-C." (PMID 41163925, 2025).
endothelial dysfunction (continued). "Although PTX and tocotrienols may protect against endothelial dysfunction, PTX and TSB did not significantly change vWF immunoreactive areas." (PMID 23894340, 2013). "Despite the absence of data on endothelial function, such as PAI-1, von Willebrand factor, or a disintegrin-like metalloproteinase with thrombospondin type 1 motifs 13 (ADAMTS 13) in our study, endothelial dysfunction might be induced by HSCTs among the AKD patients." (PMID 30842899, 2019).
COVID-19 (411 papers, 2020 to 2026). A disease caused by infection with severe acute respiratory syndrome coronavirus 2. "CoV-2 infection is not only associated with increased plasma levels of VWF but also was reported to have a qualitative impact on the VWF activity, specifically enhancing its adhesive properties, such as collagen binding." (PMID 34575297, 2021). "Severe coronavirus disease 2019 (COVID-19) infection is associated with endothelial pro-inflammatory and pro-thrombotic state that may be caused by release of VWF and P-selectin." (PMID 35528838, 2022). "Persistent endothelial activation in the setting of COVID-19 is associated with increased levels of von Willebrand factor (vWF) and soluble thrombomodulin, which lead to a loss of venous compliance and increased venous congestion." (PMID 40806356, 2025). "COVID-19-associated endotheliopathy has also been linked to increases in von Willebrand factor (vWF) release, platelet activation, and hypercoagulability, which collectively drive venous, arterial, and microvascular thrombosis." (PMID 40002898, 2025). "Regarding the association between COVID-19 and coagulation abnormalities, data from the literature suggest that while the von Willebrand factor (vWF) is upregulated, ADAMTS13, a metalloprotease that cleaves high-molecular-weight vWF, is downregulated." (PMID 40564774, 2025). "Elevated levels of VWF have been linked to the increased frequency of thromboembolism events in COVID-19 patients." (PMID 40224277, 2025). "This suggests a potential role for vWF, which acts as a marker of SI, in COVID-19 associated coagulopathy." (PMID 41311551, 2025). "Patients with severe COVID-19 have been found to have significantly higher plasma VWF antigen (VWF:Ag) and activity (VWF:RCo and VWF:CB) levels, which is consistent with the idea that severe COVID-19 is linked to notable endothelial cell activation." (PMID 40362344, 2025). "The roles of factor VIII and vWF in the pathogenesis of COVID-19-associated coagulopathy are particularly important." (PMID 41516301, 2025). "•VWF and ADAMTS13 imbalance: One of the most critical aspects of COVID-19-associated microangiopathy is the imbalance between VWF and ADAMTS13, a metalloprotease responsible for cleaving VWF to prevent excessive clot formation." (PMID 40850218, 2025). "Our aim here was to study the association between critical COVID-19 disease-related outcomes and markers from the VWF gene." (PMID 41585277, 2025). "Non-coding ABO variants associated with thrombosis, von Willebrand factor levels, and COVID-19 severity reveal topological proximity to ADAMTS13 in endothelial cells." (PMID 41311061, 2025). "Greater severity of COVID-19 is associated with higher levels of thromboinflammatory markers (VWF ag/ADAMTS 13 activity level), the latter which can be reduced by PEX." (PMID 39043682, 2024). "An MR investigation involving 12 coagulation factors and COVID-19 severity reported that VWF is strongly correlated with COVID-19 susceptibility and hospitalization." (PMID 38742101, 2024). "Patients with severe/critical COVID-19 symptoms are at a higher risk of extracorporeal coagulation during hemodialysis, which is associated with the upregulation of the vWF/FBLN5 signaling pathway." (PMID 38649864, 2024). "Severe COVID-19 is also associated with elevated endothelial activation, hypercoagulability, and the presence of von Willebrand Factor (vWF)." (PMID 37938797, 2024). "Severe respiratory symptoms of COVID-19 illness are associated with elevated D-dimer and von Willebrand Factor (vWF) levels, complement activation, and antiphospholipid antibodies." (PMID 39334765, 2024). "For example, in COVID-19 patients, this imbalance resulted in large VWF multimers, which were linked to a high thrombotic risk." (PMID 39408067, 2024). "This acute coagulation disorder is termed COVID-19-associated coagulopathy and the von Willebrand Factor potentially contributes to its development." (PMID 38745860, 2024).
COVID-19 (continued). "Local and systemic inflammation that characterizes COVID-19 activates and damages the endothelium, resulting in an elevation of von Willebrand factor (vWF) in the blood, making the vasculature more susceptible to thrombotic events." (PMID 39616228, 2024). "For example, recent histological results in lung tissue from patients with COVID-19 have provided direct evidences showing clot formation with increased staining of EC-associated vWF." (PMID 38921594, 2024). "High plasma concentrations of fibrinogen, von Willebrand factor (vWF) and D-dimer measured in these patients, suggest presence of a COVID-19-associated coagulopathy." (PMID 38643179, 2024). "Plasma von Willebrand factor (vWF) is increased in COVID-19 patients with high concentrations associated with severe disease." (PMID 37108759, 2023). "It has been proposed that vWF should be seen as a predictive factor for thrombotic risk and endothelial injury in COVID-19." (PMID 38107577, 2023). "Circulating EVs loaded with tissue factor, VWF, and many other thrombosis and coagulopathy mediators from critically ill COVID-19 patients were observed to cause endothelial apoptosis." (PMID 36634048, 2023). "For diagnosis of COVID-19; LA-1 has better diagnostic accuracy than VWF (87.1% vs. 73.8%) with AUC = 0.88." (PMID 36138306, 2023). "As expected, the von Willebrand factor plays a role in COVID-19-associated coagulopathy, as its levels and activity increase in severe infection." (PMID 37893186, 2023). "vWF has previously been reported to be increased in COVID-19 patients and is associated with disease severity." (PMID 37175392, 2023). "Exposing endothelial cells to plasma from COVID-19 patients for 1 h causes decreased viability and increased secretion of vWF." (PMID 37526812, 2023). "COVID-19 group patients with Type 2 Diabetes Mellitus (DM2) were associated with a higher expression of vWF (p = 0.032)." (PMID 36992415, 2023). "The objective of this study was the determination of the concentration and activity of vWF in patients with COVID-19, and the search for new diagnostic indices." (PMID 38132876, 2023). "Endotheliopathy, which is defined by high vWF antigen concentrations, has been linked to poor prognoses in COVID-19 patients, thus confirming the medical importance of vWF in ARDS and similar medical conditions." (PMID 37958192, 2023). "It has also been proposed that COVID-19-associated endotheliopathy results in augmented vWF release, platelet activation, and hypercoagulability, leading to venous, arterial, and microvascular thrombosis." (PMID 36851722, 2023). "COVID-19-caused inflammation of the endothelium initially upregulates the activity of von Willebrand factor (vWf) and factor VIII, leading to inadequate balance by the otherwise often normal levels of its depolymerase (ADAMTS-13)." (PMID 37763010, 2023). "In patients with pulmonary damage of non–COVID-19 causes, VWF staining was as detectable in desquamated cells as it was in COVID-19 lungs." (PMID 37333991, 2023). "A higher FVIII and higher Von Willebrand factor (VWF) are also specific features of COVID-19-associated coagulopathy." (PMID 37628963, 2023). "FVIII and VWF which are part of the intrinsic pathway of coagulation are also linked to inflammation and are known to be raised in COVID-19 patients." (PMID 36607961, 2023). "VWF was also associated with platelet-enriched characteristic NETosis thrombi, which were also more prevalent in COVID-19 samples." (PMID 37333991, 2023). "Patients with COVID-19 present coagulopathy and endotheliopathy, characterized by elevated levels of von Willebrand factor (vWF) and soluble thrombomodulin, which has been associated with disease severity and mortality." (PMID 37376587, 2023). "A retrospective analysis showed that plex reduced the excess of vWF and increased the activity of ADMTS 13, leading to the adjustment of the ratio of ADMTS 13 / vWF and thus reducing the risk of immunothrombosis in COVID-19 patients." (PMID 37958192, 2023).